IL17A (interleukin 17A)
Diseases named in the same sentence as IL17A in open-access papers (continued):
Sharing a sentence is not in itself a finding about the gene and the disease.
asthma (continued). "In some patients with asthma is found an increase of IL-17A that seems associated with more severe forms of asthma." (PMID 32610544, 2020). "Airway tissues from patients with severe asthma demonstrated increased expression of Th17-associated cytokines, IL-17A, and IL-17F, together with increased expression of IL-8 and excess neutrophilia." (PMID 32670268, 2020). "In the IL17A, the T allele of rs1974226 was positively associated with asthma (OR: 1.37; 95% CI 1.02–1.82)." (PMID 31168303, 2019). "IL-17A is associated with severe asthma and requires IL-23R signaling, which is negatively regulated by let-7f miRNA in CD4+ lymphocytes." (PMID 31071965, 2019). "The T allele of rs1974226 in IL17A was positively associated with asthma (OR: 1.37; 95% CI 1.02–1.82)." (PMID 31168303, 2019). "To further expand our understanding of glucocorticoid action, we used cells from healthy individuals who respond to dexamethasone by increases in IL-10 and IL-17A but are devoid of any confounding asthma-associated defects." (PMID 30598515, 2019). "Our previous studies identify glucocorticoid-induced IL-17A as a feature of SR severe asthma, but in this study, we address the underlying mechanisms and single-cell phenotyping." (PMID 30598515, 2019). "The association of IL-17A with the various asthma phenotypes, therefore, warrants further investigation." (PMID 31221987, 2019). "Increased expression of IL-17A has been linked to inflammatory diseases such as asthma, cystic fibrosis, and COPD in the airway, as well as inflammatory bowel disease, and it appears to play an important protective role against infection." (PMID 31426531, 2019). "While excessive production of cytokines in lung tissue is sufficient to explain most pathogenic features of asthma, expression level of many cytokines such as IL-10 and IL-17A in blood cells needs to be investigated." (PMID 30915130, 2018). "Recent evidence indicates that Th2 cytokines (such as IL-5 and IL-13) and other T-cell associated cytokines (such as IL-22 and IL-17A) are involved in allergic airway inflammation in asthma." (PMID 29922162, 2018). "Airway inflammation in severe and persistent asthma is associated with IL17A; and Th17 cells play a critical role in the activation and recruitment of neutrophils." (PMID 29724254, 2018). "Neutrophils and IL-17A have been linked mechanistically in models of allergic airways disease and have been associated with asthma severity." (PMID 27746241, 2017). "In three meta-analyses, the higher asthma risk was associated with IL17A rs819303620, rs227591621 and rs471199822 polymorphisms." (PMID 28916742, 2017). "Animal model studies have also established a causative link between Th17 cells and increased levels of IL-17A and IL-17F with glucocorticoid-insensitive asthma." (PMID 28628664, 2017). "CXCL-1, IL-5, IL-8, and IL-17A were positively associated with Difficult-to-Control asthma, while IL-4 and IL-13 were positively associated with Easy-to-Control asthma." (PMID 28686637, 2017). "Given the association of IL-17A and IL-5 with Difficult-to-Control asthma in African American children in our inner-city population, therapeutics targeting IL-17 and IL-5 should be considered." (PMID 28686637, 2017). "The IL-17A is a pro-inflammatory cytokine which induced IL-8 causing increased neutrophil influx to the lung; this cytokine also involved in asthma severity, airway remodeling and Treg suppression." (PMID 29182623, 2017). "An association between IL-17A and neutrophilic airway inflammation has also been established in murine asthma models." (PMID 28245275, 2017). "Th17-associated cytokines IL-17A and IL-17F were reported to exist in severe asthma and were correlated with disease severity." (PMID 26739627, 2016). "Recently, an increased level of IL-17A in sputum and serum has been reported in patients with severe asthma, which is associated with neutrophilic airway inflammation." (PMID 26418032, 2015).
asthma (continued). "Patients with severe asthma are highly susceptible to viral infections leading to acute exacerbation of asthma symptoms, and have a higher level of IL-17A in induced sputum and bronchial biopsies." (PMID 26418032, 2015). "Th2 immune responses are linked primarily to mild and moderate asthma, while Th17 cells, Interleukin-17A (IL-17) and neutrophilia have been implicated in more severe forms of disease." (PMID 25123451, 2014). "Th17 cells and their prime effector cytokine, IL-17A (hereafter referred to as IL-17), have more recently been implicated in asthma pathogenesis." (PMID 25123451, 2014). "Increased airway hyperreactivity in response to methacholine in patients with asthma positively correlates with IL-17A levels in the sputum and a polymorphism in IL-17F that results in a loss-of-function mutation is inversely related to asthma risk." (PMID 25177863, 2014). "Severe asthma is also associated with increased IL-17A production and studies in experimental models suggest a critical role for complement-mediated regulation of the IL-23-TH17 axis by enhancing IL-13-driven responses." (PMID 24223970, 2013). "We also observed increased numbers of IL-17A + neutrophils in peripheral blood of asthmatic patients particularly in those suffering from fungal allergy-associated asthma." (PMID 23822853, 2013). "In another animal study, asthma-susceptible mice were intratracheally exposed to IL-17A, IL-13, or a combination of both to elucidate the cross-regulation between IL-17A and Th2 responses during the development of airway inflammation." (PMID 24454477, 2013). "While Th2 cytokines are involved in milder forms of allergic asthma, Th17 cytokines (IL-17A, IL-17 F and IL-22) are more strongly associated with severe, difficult to treat asthma." (PMID 24283210, 2013). "Recently, it has been also reported that IL17A -197 AA homozygote is associated with several asthma-related traits and confers genetic susceptibility to childhood asthma in Chinese." (PMID 22827846, 2012). "Increased IL-17A has been associated with neutrophilic airway inflammation in murine asthma models and in human studies." (PMID 22848348, 2012). "The same report demonstrated that mice deficient in C5 produced significantly more IL-17A during experimental asthma." (PMID 23316190, 2012). "Considering the pathogenic role that IL-17A-producing ST2+ cells may play in refractory asthma, future studies will need to better clarify the role of IL-18 in the regulation of this IL-17A+ ST2+ ILC2 population." (PMID 40777291, 2025). "Moreover, steroid resistance in asthma has been strongly associated with neutrophilic inflammation and elevated IL-1β levels, which drive Th17 cell differentiation and IL-17A production, a pathway known to diminish steroid responsiveness." (PMID 41445736, 2025). "Th17-derived IL-17A subsequently acts on the epithelium to induce the production of chemokines like IL-8, recruiting neutrophils—a process closely associated with neutrophilic inflammation in severe and steroid-resistant asthma." (PMID 41278223, 2025). "For example, IL-17A, a member of the IL-17 cytokine family, is strongly associated with asthma." (PMID 40061938, 2025). "IL-17A is associated with neutrophil recruitment and activation in the lung of asthma." (PMID 39902293, 2024). "Given that IL-17A is associated with severe asthma and neutrophil infiltration, it suggests that SLC26A4 expression might peak in patients with severe asthma." (PMID 39100210, 2024). "Because according to our results, despite the increase in the mean serum level of the Total IgE and IL-17A in the patients with asthma, increased serum levels of Total IgE in subtypes of asthma are associated with decreased serum levels of IL-17A and vice versa." (PMID 38660682, 2024). "Asthma-associated serum cytokines (IL-13 and IL-17A) were modulated by oral ginger." (PMID 39770492, 2024).
asthma (continued). "Similarly, HDM-induced asthma accompanied with obesity enhanced neutrophilic airway inflammation and airway hyperresponsiveness linked with higher levels of IL-17A and MIP2." (PMID 38203630, 2023). "Moreover, IL-17A is a pro-inflammatory cytokine implicated in asthma pathogenesis, whereas IL-17A-enriched NETs can exert a potent fibrotic role." (PMID 37626601, 2023). "Conversely, IL-17F protein and mRNA seem more closely linked to the severity of asthma than IL-17A." (PMID 37115755, 2023). "Indeed, our data are consistent with those of previous studies, showing that IL-17A is a key mediator that is implicated in neutrophilic responses in adult asthma." (PMID 37626601, 2023). "OVA-induced asthma associated with obesity resulted into an increase in iNOS-expressing macrophages and neutrophils, increased levels of IL-4, IL-9, IL-17A, leptin and IFN-γ in the lung, higher goblet cell hyperplasia, and elevated mast cell influx into the lung and trachea." (PMID 38203630, 2023). "Additionally, supplementation with AGs resulted in a statistically significant decrease in plasma IL-17A, suggesting a reduction in neutrophilic inflammation, a hallmark of the obese asthma phenotype." (PMID 37367676, 2023). "The literature available on the association of IL17Ars2275913, localized in the promoter region, with the expressionlevel and cytokine activity of IL-17A are very inconsistent.Thus, an association between the SNP and susceptibilityto asthma in children has been noted, i." (PMID 37465198, 2023). "Additionally, Th17-associated IL-17A is dominant in neutrophilic asthma, and its excessive accumulation leads to asthma aggravation." (PMID 36329800, 2022). "Moreover, asthma severity has been linked with more elevated levels of IL-17A in these sputum, nasal and bronchial biopsies and serum." (PMID 35773318, 2022). "Increased expression of the Th17-derived cytokine IL-17A has been observed in sputum, airway tissue biopsies, and serum from asthmatic patients and was positively associated with a more severe asthma phenotype and neutrophilic inflammation." (PMID 36140430, 2022). "Besides, IL-17A is a potent neutrophil chemotactic agent, which explains the association between obesity-induced asthma and neutrophilia." (PMID 36466877, 2022). "Excess production of IL-17A has been linked to the risk of developing severe asthma." (PMID 35769576, 2022). "IL-17A was also implicated in glucocorticoid resistant asthma." (PMID 33717165, 2021). "Previous studies have shown that IL-6 and IL-17A are associated with airway remodeling in asthma." (PMID 34526979, 2021). "High IL‐17 expression, including IL‐17A and IL‐17F, has been implicated in asthma pathogenesis." (PMID 33747463, 2021). "Chitinase-like proteins are molecules strongly associated with severe asthma, neutrophilia and IL-17A.33–36 Following exposure to DRA allergen, mRNA expression of murine chitinase-like genes Chil1, Chil3 and Chil4 were upregulated in both BALB/c and C57BL/6 mice compared with PBS controls." (PMID 33587776, 2021). "However, the ability of IL-17A to then suppress type-2 responses, reveal an important feedback loop that must go awry during severe asthma and other type-2 conditions in which IL-17A plays a damaging and pathogenic role." (PMID 32636457, 2020). "However, glucocorticoids also enhance the synthesis of IL-17A by PBMCs, which, in excess, is associated with increased asthma severity and glucocorticoid-refractory disease." (PMID 30598515, 2019). "Of note, IL-17A has been implicated in the pathogenesis of asthma." (PMID 29883409, 2018). "Additionally, it has been recently demonstrated that IL-17A levels in bronchial biopsies from asthma patients are associated with disease severity." (PMID 28199353, 2017). "Since expression of IL-17A is a hallmark of severe asthma correlated with infiltration of neutrophils, pendrin may be maximally expressed in severe asthma patients." (PMID 29359006, 2017).
asthma (continued). "We therefore hypothesized that intraepithelial neutrophils, together with elevated IL-17A and IL-22, would be associated with worse asthma severity." (PMID 27746241, 2017). "Increased IL-17A has been implicated in severe asthma by prior studies." (PMID 28686637, 2017). "Levels of IL-17A in sputum, nasal wash, and plasma as well as levels of circulatory T cells expressing IL-17 were studied in children with moderate asthma, and it was suggested that IL-17 could be associated with asthma severity." (PMID 28725641, 2017). "IL-17A has also been implicated in lung diseases including asthma." (PMID 26201093, 2015). "Our data suggest that neonatal S. pneumoniae infection may promote the development of adulthood asthma in association with increased IL-17A production." (PMID 25816135, 2015). "IL-17A), which is thought to cause severe asthma and induce neutrophilic inflammation." (PMID 24959003, 2014). "Considering the inflammatory properties of IL-17A, this study suggests that it could increase susceptibility to atopy and asthma." (PMID 24141678, 2013). "Th17 cells and IL-17A have recently been implicated in the pathogenesis of AD and asthma." (PMID 22848348, 2012). "Moreover, all healthy individuals had low to undetectable IL-17A and IL-8 mRNA levels in their sputum cells, which makes increased IL-17A or IL-8 mRNA levels potentially useful as a diagnostic aid in asthma." (PMID 17083726, 2006). "In addition, there are studies reporting that elevated levels of IL-17A are associated with severe asthma and increase asthma exacerbations, and thus, IL-17A might shape the progression of the disease." (PMID 37626601, 2023). "Furthermore, loss of congenital AHR was observed in obese mice deficient in IL-17A, and the gut microbiota may contribute to obesity-related asthma by altering IL-17A." (PMID 38292857, 2023). "Inflammatory cytokines could promote asthma airway inflammatory cells infiltration, and Th1 inflammatory cytokines (IFN-γ, TNF-α) or Th17 inflammatory cytokines (IL-17A) are more likely to be associated with steroid-resistant asthma (Hansbro, Kaiko & Foster, 2011)." (PMID 35602900, 2022). "MPO is a marker of neutrophil activity, and the correlation analysis suggested that MBD2 might be involved in the development of asthma by mediating the differentiation of Th17 cells, which secrete the cytokine IL-17A to chemotactic neutrophils into the airway and causing chronic inflammation." (PMID 34692717, 2021). "IL-17A is associated with neutrophil recruitment, which is a hallmark of severe asthma, and may play a direct role in the enhanced severity experienced by patients with fungi associated asthma." (PMID 33324573, 2020). "In addition, polymorphisms in the IL-17A gene related to asthma risk have been reported." (PMID 23956763, 2013). "Finally, we tested the effect of Inhaled Corticosteroids (ICS) and long-actingβ2agonists (LABA) in both an in vitro and in vivo approach in order to provide new therapeutic strategies to control the inflammation associated with Th17 producing IL-17A in children with AR and concomitant asthma." (PMID 23573194, 2013). "Mechanistic studies have established that non-T2 asthma involves prominent activation of Th1 and Th17 responses, with key roles for IL-6, IL-17A, and TNF-α in driving neutrophilic inflammation and airway hyperresponsiveness." (PMID 41601686, 2026). "IL-17A exerts its effects on multiple cell types, including airway smooth muscle cells, endothelial cells, and fibroblasts, and is arguably best known in asthma for mediating the recruitment of neutrophils to the lungs." (PMID 40337866, 2025). "In the DOG-induced model of asthma, airway inflammation is mainly driven by Th17 cytokines (IL-17A and IL-22)." (PMID 40082266, 2025). "IL-17A has also been shown to contribute to mucus production and AHR, and is associated with neutrophilic inflammation and severe asthma." (PMID 40674143, 2025).
asthma (continued). "On the other hand, low-profile T2 asthma involves the activation of T helper 1 (Th1) and T helper 17 (Th17) cells, leading to increased levels of interleukin-17A (IL-17A)." (PMID 40649123, 2025). "Ginger improved multiple symptom-related endpoints, including Asthma Control Test (ACT) scores and asthma-specific quality of life, while modulating IL-13 and IL-17A levels." (PMID 41305557, 2025). "Exogenous IL-23 treatment restored the production of IL-17A in asthma TLR6-/- mice, significantly reducing airway hyperresponsiveness, inflammation and pulmonary fungal burden." (PMID 40672946, 2025). "The findings of this study provide a comprehensive insight into the interplay of LL-37 and IL-17A/F and are relevant to the immunobiology of respiratory disease such as severe asthma and COPD that are characterized by airway inflammation with neutrophilia." (PMID 40410820, 2025). "While SCF/c-Kit signaling has been shown to regulate mast cell and ILC2 functions, which are primarily associated with eosinophilic inflammation, our study reveals an unexpected role for SCF in IL-17A production and neutrophilic inflammation during asthma." (PMID 40674143, 2025). "ILC1s, together with ILC3s, induce M1 macrophage polarization through IFN-γ and IL-17A, and contribute to asthma pathogenesis." (PMID 40355861, 2025). "Following their differentiation, Th17 cells release various cytokines, notably IL-17A, IL-17F, IL-22, and IL-21, with IL-17A being the most extensively studied in the context of asthma pathogenesis." (PMID 40564060, 2025). "Increased IL-17A expression correlates with neutrophilic inflammation, a feature of corticosteroid-resistant asthma, suggesting that estrogen’s role extends beyond type 2 inflammation." (PMID 40508095, 2025). "Taken together, our study revealed a significant upregulation of SCF expression in patients with asthma, which correlated with the expressions of IL-17A and MPO." (PMID 40674143, 2025). "Th17 cells and IL‐17A levels are increased in asthma, particularly in the airways of patients with neutrophil or severe therapy‐resistant asthma." (PMID 40016948, 2025). "In chronic models of asthma, IL-17A promotes fibroblast proliferation, undermines regulatory T cell-mediated suppression, and directly induces contraction of bronchial smooth muscle cells." (PMID 40732309, 2025). "Secukinumab, a human antibody that targets IL-17A, and brodalumab, an antibody that targets IL-17RA, have been developed and tested in severe uncontrolled asthma." (PMID 41145900, 2025). "Our results have shown that the increased expression of CTSC also promoted the infiltration of inflammatory cells and the production of inflammatory factors (e.g., IL-5, IL-13, and IL-17A) in the HDM-induced asthma model and SA model." (PMID 39436705, 2024). "In experimental asthma models driven by house dust mites (HDMs) or ozone exposure, IL-17A contributes to airway remodeling by promoting fibroblast proliferation and counteracting the anti-inflammatory functions of regulatory T cells." (PMID 39664985, 2024). "ELISA was used to measure concentrations of cytokines (IL-1β, IL-18, IL-17A, and IL-10) in serum samples collected from asthma patients and healthy individuals." (PMID 38849380, 2024). "In this study, we evaluated the effects of stigmasterol on inflammatory cytokines and the TGF-β1/Smad2 and IL-17A signaling pathway in an ovalbumin (OVA)-induced asthma mouse model." (PMID 38579176, 2024). "The concentrations of IL-10, IL-13, and IL-17 A in the asthma group were significantly lower than those in the control group (IL-10: P = 0.043; IL-13: P = 0.014; IL-17 A: P = 0.026)." (PMID 38218943, 2024). "The findings of the two‐way analysis of variance indicated that baseline airway resistance, the number of neutrophils, inflammation score, and IL‐17A levels were notably elevated in obesity‐related asthma mice (HDM‐induced models) compared to lean asthma mice." (PMID 38286741, 2024).